AHR (aryl hydrocarbon receptor)
Diseases named in the same sentence as AHR in open-access papers (continued):
Sharing a sentence is not in itself a finding about the gene and the disease.
breast carcinoma (continued). "One study used 5 different ligands and 6 different breast cancer cell lines to show that these AhR ligands inhibited breast cancer cell growth, and this was supported by limited KO studies in which loss of the AhR resulted in loss of AhR ligand -dependent growth inhibition." (PMID 36428667, 2022). "Several studies have since shown that chemical exposure and AhR activation affect processes of mammary gland differentiation, disrupting pregnancy-related differentiation and milk production, and increasing the risk of breast cancer." (PMID 36588678, 2022). "We hypothesized that high tumor levels of AhR would be associated with good prognosis in breast cancer, but that the prognostic impact might depend on the subcellular AhR localization, treatments, as well as body constitution." (PMID 34094928, 2021). "In addition, human breast cancer-associated fibroblasts upregulate the canonical AhR target gene, CYP1B1, and proliferate in response to treatment with the AhR ligand, 3-methylcholanthrene." (PMID 33763068, 2021). "In addition, in DMBA-induced murine mammary tumors, it has been described that there is a high expression of AhR, the oncogenes cyclin D1 and c-myc, in association with NF-κB and Wnt signalling." (PMID 32722276, 2020). "Again, although these GSEA analyses do not prove causality, they are consistent with a role for the AHR in regulation of invasion-associated genes and suggest that AHR inhibition would be a useful strategy for breast cancer therapy as suggested for other cancer types." (PMID 29735912, 2018). "Previously, we postulated that constitutive AHR activity, driven in part by the production of μM quantities of the endogenous tryptophan-derived ligands kynurenine and xanthurenic acid, is causally linked to breast cancer invasion." (PMID 29735912, 2018). "Although the mechanism behind the finding of the present study is not fully understood, the current study provides new insight into how the CYP1A2 rs762551 combined with the functional AhR Arg554Lys variant is linked to prognosis in AI-treated breast cancer patients." (PMID 27029552, 2016). "Also, TCDD disrupts IGF signaling in breast cancer cells via association of AHR with the CCND1 gene promoter." (PMID 27563312, 2016). "Furthermore, reduced CYP1A1 enzymatic activity has been linked to constitutive activation of the AhR and resistance of breast cancer cells to apoptosis induced by DMBA." (PMID 26715507, 2015). "Collectively, this report provides evidence that drugs that target the AHR may reduce breast cancer risk in the context of human obesity." (PMID 24171117, 2013). "In any case, it will be important to investigate whether individuals with nuclear AhR overexpression in benign mammary tissue are at a higher risk to develop breast cancer." (PMID 20565777, 2010). "Since one of the main objectives of this study was to investigate the cause for AhR overexpression in breast cancer cells, we wanted to have at least another example of mammary epithelial cells developing AhR overexpression for the purpose of confirming the effect of E2." (PMID 19604390, 2009). "Moreover, in-depth analysis of breast cancer, especially the basal-like breast cancer for the correlation between the levels of PD-L1 or AHR and the infiltration of Treg cells revealed that high levels of PD-L1 and AHR were associated with increased infiltration of Treg cells in patients." (PMID 39690159, 2024). "Thus, AhR inhibition may allow for enhanced IFN-I production upon PARPi in BRCA1-deficient breast cancers, most of which are of TNBC origin, and may represent a therapeutically viable strategy to enhance PARPi efficacy." (PMID 38459088, 2024). "Activation of the aryl hydrocarbon receptor (AhR) through environmental exposure to chemicals including polycyclic aromatic hydrocarbons (PAHs) and polychlorinated dibenzo-p-dioxins (PCDDs) can lead to severe adverse health effects and increase the risk of breast cancer." (PMID 36588678, 2022).
breast carcinoma (continued). "Maternal exposure to AhR agonists has been proposed as a risk factor for breast cancer in the offspring through epigenetic inhibition of the tumor suppressor BRCA-1 (Breast cancer 1), whereas dietary AhR antagonists may exert protective effects against such disease." (PMID 27243009, 2016). "Therefore, understanding if changes in expression and/or activation of the AhR are associated with somatic inactivation of the BRCA-1 gene may provide clues for breast cancer therapy." (PMID 26715507, 2015). "We could clearly establish in the current study that E2-selection causes induction of AhR overexpression in two MCF breast cancer cell lines, and that such a phenomenon is accompanied with increased cell proliferation that is significantly dependent on the presence of AhR." (PMID 19604390, 2009). "In breast cancer, proteasome-dependent degradation of ERα is caused by the induction of TCDD, which promotes the formation of the AhR complex." (PMID 41301867, 2025). "The current study demonstrated significant interactions between AHR genotypes, lifestyle and systemic adjuvant treatments with respect to clinical outcomes in breast cancer." (PMID 40646277, 2025). "In MCF-7 breast cancer cells, quercetin functions as an AhR antagonist, whereas in HepG2 liver cells, it can induce AhR activation and stimulate CYP1A1 gene expression following 24 h of exposure." (PMID 41009721, 2025). "TH downregulates ROS levels and HIF-1α expression in MCF-7 breast cancer cells and can bind to the aryl hydrocarbon receptor (AhR) at high concentrations." (PMID 40298838, 2025). "The purpose was to perform a comprehensive analysis of the prognostic impact of AHR genotypes, lifestyle and different adjuvant treatments in patients with primary breast cancer." (PMID 40646277, 2025). "AHR has also been shown to repress IFN-I independently of PARP7 by inducing the proteolytic degradation of STING, and pharmacologic inhibition of AHR using BAY2416964 restored STING activity in breast cancer cell lines." (PMID 41432900, 2025). "If confirmed, these results emphasise the importance of considering pharmacogenomics, including AHR genotypes, for more personalised lifestyle recommendations and to better guide selection of adjuvant breast cancer treatment." (PMID 40646277, 2025). "In conclusion, different AHR genotypes were found to significantly interact with lifestyle factors and adjuvant treatments with respect to breast cancer prognosis." (PMID 40646277, 2025). "AhR activation promotes resistance to chemotherapy in prostate and breast cancers, and choriocarcinoma." (PMID 39852970, 2025). "For example, IDO mediates relevant cancers such as breast cancer and ovarian plasma adenocarcinoma through the Trp-AhR pathway, while in the testis, it mediates testicular immune privilege, preventing the body’s immune cells from attacking their own antigens." (PMID 41282989, 2025). "Doxorubicin activates AhR signaling in the cardiomyocytes of adult rats, but its effect on human breast cancer cells is less well studied." (PMID 40478625, 2025). "In vitro studies then confirmed that antioxidants led to AhR activation with increased CYP1B1 levels in two breast cancer cell lines." (PMID 40646277, 2025). "Adipocytes also contribute to Trp metabolism in breast cancer by metabolizing Trp and releasing Kyn, which activates the AhR in mammary epithelial cells, promoting malignant transformation." (PMID 41332472, 2025). "In the absence of estrogen receptors, 4OHT can induce the expression of AhR target genes involved in estradiol metabolism, cell proliferation, and metastasis in breast cancer cell models." (PMID 41440753, 2025). "AhR‐mediated IDO2 expression seemingly contributes to a tumor‐promoting microenvironment in breast cancer." (PMID 41332472, 2025). "The importance of AHR, PD-L1, and Tregs in this context also provides a valuable prognostic indicator for breast cancer, given that these factors are correlated with patient outcomes." (PMID 39690159, 2024).
breast carcinoma (continued). "The Cancer Genome Atlas dataset (Pan-Cancer Atlas) from patients with breast cancer showed a significant positive correlation between AhR and ZEB1." (PMID 39311710, 2024). "Altogether, these observations strongly suggest the activation of AhR in GC, as previously reported in breast cancer." (PMID 39200369, 2024). "Our study showed that increased activity of the aryl hydrocarbon receptor (AHR) in lung macrophages plays a crucial role in establishing the immunosuppressive PMN in breast cancer." (PMID 39690159, 2024). "In our study, we observed a significant and temporary increase in AHR activity in lung macrophages prior to breast cancer metastasis." (PMID 39690159, 2024). "The ongoing hyper-activation of the AhR in breast cancers and its ability to control many oncogenic pathways builds upon the role of AhR in progression of this disease." (PMID 38974991, 2024). "The EROD activity assay measured the effects of flavonoids on AHR’s activity in human breast cancer cells (MCF7)." (PMID 39204085, 2024). "Patients with low AHR expression exhibited better OS compared to those with higher AHR expression, suggesting a potential role of AHR in diagnosing breast cancer progression." (PMID 39690159, 2024). "To investigate the clinical relevance of our findings, we assessed AHR+ F4/80+ macrophages in patients suffering breast cancer lung metastasis." (PMID 39690159, 2024). "Particularly, in breast cancer, AhR is overexpressed compared to normal tissue and its activation is associated with an increased expression of drug transporters producing drug resistance." (PMID 38745771, 2024). "For example, exposure of estrogen receptor (ER) positive breast cancer cells to low doses of PAHs mixture activated AHR and overexpressed CYP1 isoforms, which correlated with increased expression of antiapoptotic and antioxidant proteins." (PMID 38982523, 2024). "In a mouse model of breast cancer, our research has uncovered a significant role for the AHR in lung macrophages, which is induced by GM-CSF secreted by 4T1 breast cancer cells." (PMID 39690159, 2024). "The anticancer mechanisms of PMFs against breast cancer were also reviewed, including the estrogen activity, cytochrome P-450 enzyme system, and arylhydrocarbon receptor (AhR) inhibition, along with various molecular targets and potential anticancer effects." (PMID 38188169, 2024). "DATS inhibited proliferation, ROS formation, 8-OHdG levels, AhR expression and clonogenic formation in breast cancer cells compared to B [a] P group." (PMID 39403128, 2024). "The metabolism of environmental toxins by the AhR lends credence to the initiation of breast cancer by a fat-soluble xenobiotic element that was metabolized to a DNA-damaging compound." (PMID 38974991, 2024). "Screening studies of pharmaceutical-derived AHR modulators have been commonly conducted in breast cancer cell lines, such as MCF7 cells, due to their well-characterized AHR function and high responsiveness to its agonists." (PMID 39204085, 2024). "By regulating the expression of genes associated with cell differentiation, drug resistance, and inflammation induction, AHR’s activity has a significant impact on cancers such as human melanoma, breast cancer, liver cancer, lung cancer, and glioblastoma." (PMID 39204085, 2024). "In breast cancer patients, the expression of AHR and PD-L1 was correlated with increased Treg cell infiltration, and higher levels of AHR were associated with a poor prognosis." (PMID 39690159, 2024). "Studies have found that in breast cancer cells, the AhR agonist Aminoflavone pro-drug (AFP464) can inhibit the formation of breast tumor spheres and suppress TIC growth by inhibiting ITGA6 expression in breast cancer." (PMID 39239559, 2024). "There is a report that AHR-mediated over expression of miR-212/132 cluster reduced migration and invasion of breast cancer cells by suppressing mRNA of pro-metastatic transcription factor SOX-4." (PMID 39125717, 2024).
breast carcinoma (continued). "Collectively, this study suggests that the increased AHR levels in lung macrophages, induced by GM-CSF from primary breast cancer, are crucial for establishing an immunosuppressive environment for breast cancer cell colonization and regrowth." (PMID 39690159, 2024). "Such a crosstalk through altered p300 recruitment to Nrf2-regulated target genes was shown, for e.g., in ER-positive MCF7 breast cancer cells treated with racemic sulforaphane, a dual AhR and ERα activator, 3,3′-diindolylmethane, and TCDD, or E2." (PMID 39339278, 2024). "We have explored the link between the AhR and breast cancer in the development of therapeutic small molecules." (PMID 38974991, 2024). "In support of the role of AhR in cancer development, researchers have identified upregulated expression of AhR in human and rodent tumors, such as breast cancer, lung adenocarcinoma, and ovarian cancer, implicating the role of AhR in tumor progression." (PMID 38448800, 2024). "We, and others have noted that the activation of the AhR pathway by ligands such as 1-7 results in specific cytotoxicity towards breast cancer cell lines." (PMID 38974991, 2024). "In breast cancer, AHR shapes the tumor microenvironment and modifies immune tolerance, whilst in lung cancer, AHR is involved in the regulation of cell proliferation, angiogenesis, inflammation, and apoptosis." (PMID 38982523, 2024). "During breast cancer progression, AHR expression in lung macrophages peaked at ~12 days after 4T1 cell inoculation, followed by a subsequent decrease." (PMID 39690159, 2024). "In breast cancer subtypes where ER is positively expressed, AhR has been described to exert tumor suppressive functions." (PMID 38807762, 2024). "Diallyl trisulfide plays an anti-cancer role by reducing B [a] P induced oxidative stress, AhR expression and DNA damage in human breast cancer epithelial cells." (PMID 39403128, 2024). "The potency and selectivity of these compounds in breast cancers is determined by their chemical composition as well as the overexpression of AhR and SULT1A1 proteins, with the latter presenting as a potential clinical biomarker for targeted therapy." (PMID 38974991, 2024). "This phenomenon is unique and resides in the role of the AhR pathway in the initiation and progression of breast cancer." (PMID 38974991, 2024). "Ligand-induced AhR activation in endometrial cancer largely has anti-estrogenic and tumor suppressive effects, as seen in ER+ positive breast cancer." (PMID 38807762, 2024). "Lung, liver, and breast cancers are the ones represented by the highest number of AOPs and AhR activation is the most prevalent MIE." (PMID 38523647, 2024). "We also found that granulocyte-macrophage colony-stimulating factor (GM-CSF) released from primary breast cancer cells stimulated and stabilized AHR expression through signal transducer and activator of transcription 5 (STAT5) signaling." (PMID 39690159, 2024). "Our investigation on the role of AHR in the PMN of breast cancer has yielded new insights into AHR-mediated regulation of tumor metastasis." (PMID 39690159, 2024). "Leveraging this data, we sought to further explore the breast cancer selectivity and activation of the AhR/CYP1/SULT1A1 axis of a library of substituted BBQ analogues, in cell line models of the disease." (PMID 38974991, 2024). "AhR is overexpressed and constitutively active in breast cancer, where it is thought to have varying effects depending on the ligand and cell type." (PMID 38807762, 2024). "An in vitro study has shown that indoxyl sulfate, a tryptophan metabolite, acting through the aryl hydrocarbon receptor and pregnane-X-receptor, not only reduced the severity of breast cancer but also inhibited the proliferation of breast cancer cells." (PMID 39422470, 2024). "An example of this process is the widely used DMBA-induced surrogate model of breast cancer tumorigenesis in animal studies via AhR activation and metabolic bio-activation." (PMID 38974991, 2024).
breast carcinoma (continued). "To explore the contribution of AHR activity in macrophages to breast cancer metastasis to the lung, we employed the Cre-Lox recombination system to specifically delete AHR in macrophages in vivo." (PMID 39690159, 2024). "This positive link among AHR, PD-L1, and Treg cell infiltration correlates with poor prognosis for breast cancer." (PMID 39690159, 2024). "Our findings highlight the crucial role of AHR in lung macrophages in shaping a conducive pre-metastatic environment for breast cancer cells and suggest a potential target to combat metastatic diseases." (PMID 39690159, 2024). "Most evidence points to inhibitory AhR–ERα crosstalk, in which the activation of the AhR blocks ERα signaling, which in turn stops breast and endometrial cancer cells from proliferating and growing into mammary tumors." (PMID 39339278, 2024). "The aryl hydrocarbon receptor (AhR) is an emerging signaling pathway that is garnering considerable promise as a therapeutic target for certain subtypes of breast cancer." (PMID 37408267, 2023). "Inhibitory crosstalk between estrogen receptor alpha (ERα) and aryl hydrocarbon receptor (AHR) regulates 17β-estradiol (E2)-dependent breast cancer cell signaling." (PMID 37834026, 2023). "The AhR has been shown to transactivate class I heterodimeric nuclear receptors while antagonising the activation of homodimeric ones in breast cancer cells." (PMID 36899825, 2023). "In the current study, we found that toxic AhR ligands such as TCDD, BaP, and TRAP-derived PM significantly induce the expression of IDO2 in MCF-7 human breast cancer cells in an AhR-dependent manner." (PMID 37408267, 2023). "This is important since the AhR has been found to play an important role as a mediator linking inflammation and breast cancer." (PMID 37408267, 2023). "Deletion of AhR enhances the invasive capacity of the MDA-MB-231 breast cancer cells, but on the contrary decreases cell proliferation and proliferation-related genes." (PMID 37241719, 2023). "Extensive research using a broad panel of breast cancer cells has clearly indicated modulation of AhR functions by AhR ligands, including SAhRMs, as a promising strategy for drug development." (PMID 37241719, 2023). "We used chromatin immunoprecipitation with high-throughput sequencing and transcriptomics to study ERα as well as AHR coregulation in MCF-7 human breast cancer cells treated with DIM, RES, E2, or TCDD alone or E2+TCDD for 1 and 6 h, respectively." (PMID 37834026, 2023). "The focus of this study is to investigate the regulation of IDO2 expression in human breast cancer by AhR ligands, including environmental pollutants and endogenous ligands known to activate the AhR signaling pathway." (PMID 37408267, 2023). "3′,4′-dimethoxyflavone (DMF) was reported to be an effective AhR inhibitor that blocks the formation of nuclear AhR complexes in TCDD induced breast cancer cells." (PMID 37277776, 2023). "In this study, we used ChIP-sequencing and RNA-sequencing to determine how RES and DIM differentials affect ERα and AHR in MCF-7 breast cancer cells." (PMID 37834026, 2023). "Recently, an adverse outcome pathway (AOP) was proposed for breast-cancer related cell death, with AhR as the molecular initiating event (MIE), decreased apoptosis and increased motility, inflammation, and endothelial migration as cellular key events (KE)." (PMID 37696458, 2023). "For example, the naphthylamide (2-(2-aminophenyl)-H-benzo[d,e]isquinoline-1,3[2H]-dione (NAP-6) is a newly identified AhR agonist with anti-breast cancer properties." (PMID 37241719, 2023). "Activated AHR inhibits many ER-dependent responses; because of this, AHR agonists have been suggested as potential therapeutic targets for ERα+ breast cancer." (PMID 37834026, 2023).